FTX (FTX transcript, XIST regulator)
Diseases named in the same sentence as FTX in open-access papers (continued):
Sharing a sentence is not in itself a finding about the gene and the disease.
cancer (continued). "We compared the FTX expression between multiple cancers and normal tissues with using TCGA dataset." (PMID 35027040, 2022). "Many of the top oncogene candidate lncRNAs (MIR100HG, LINC01268, FTX, etc.)were reported to promote cell growth or proliferation in different cancer types, suggesting that these lncRNAs may be involved at initial stages of tumorigenesis." (PMID 36359790, 2022). "Furthermore, we used data from 4668 patients with high FTX expression and 4691 patients with low FTX expression to analyze the prognostic role of FTX in cancer." (PMID 35027040, 2022). "Moreover, we found that the expression of FTX was significantly related to the advanced stage of cancers (p < 0.05)." (PMID 35027040, 2022). "The role of FTX as an independent predictive factor for OS in patients with cancer was assessed." (PMID 33398336, 2021). "Therefore, it is necessary to conduct a comprehensive meta-analysis of the existing data to assess the correlation between FTX and clinicopathological features and survival outcomes in patients with cancer." (PMID 33398336, 2021). "Considering the wide impact of FTX in human cancer, we speculated that FTX might also exert similar expression pattern and functions in RB development." (PMID 34720057, 2021). "To evaluate the role of FTX in RB, we detected its expression levels in RB tissues and cancer cell lines, and the results showed that the expression levels of FTX were notably elevated in RB tissues compared with that in adjacent normal tissues (p < 0.01, n = 30)." (PMID 34720057, 2021). "LncRNA FTX was firstly identified in Xist gene locus and was dysregulated in many human cancers." (PMID 32176463, 2020). "LncRNA FTX has been demonstrated to inhibit the development of some human cancers." (PMID 32660465, 2020). "Three lncRNAs, LINC00665, LINC00855 and FTX, were left with their target genes involved in several pathways, one of which was miRNA in cancer pathway, indicating that they may act partly in a ceRNA network to exert their functional role." (PMID 32419983, 2020). "The aberrant expression of FTX could be a result of the progression of cancer." (PMID 35444943, 2022). "Hence, FTX might also play a potential role in other intraocular malignant tumors, and we only focused on its role in RB." (PMID 34720057, 2021). "In addition, dysregulation of FTX has been observed in a variety of cancers." (PMID 33817286, 2020). "Among the 19 TSLNRs in this study, only eight (EPB41L4A-AS2, MEG3, LINC-PINT, FTX, HCG11, HAND2-AS1, SNHG5 and TPT1-AS1) have been reported previously to be associated with malignancy, and the potential functions of the other 11 lncRNAs in human cancer remain a mystery." (PMID 30764831, 2019). "LncRNA five Prime to Xist (FTX), located at the X chromosome inactivation (XCI) center upstream of the Xist gene, has been extensively studied in tumorigenesis and cancer progression." (PMID 40342081, 2025). "FTX, locating at X-chromosome inactivation (XCI) center, is a highly conserved lncRNA and exerts important role in the biological process of cancers." (PMID 32226311, 2020). "A recent study identified FTX as an oncogenic factor in GBM that increases during radiation exposure together with NEAT1, and both these lncRNAs are involved in cancer radio-resistance." (PMID 33066171, 2020). "FTX played an oncogenic role in LUAD and contributed to cancer development via targeting miR-335-5p/NUCB2 axis." (PMID 32226311, 2020).
heart disease (1 paper, 2022). "Through these databases, the association of DE lncRNAs with heart disease was detected, especially the H19 and FTX genes were mentioned in both databases." (PMID 35415316, 2022).
metabolic disorders (1 paper, 2025). "Furthermore, lncRNA FTX has emerged as a promising therapeutic target for preserving or restoring pancreatic β-cell function, offering a potential RNA-based intervention for IUGR and its associated metabolic disorders, such as GDM." (PMID 40342081, 2025).
FTX also shares sentences with these, for which no sentence is quoted: non-small cell lung carcinoma (2 papers); oral squamous cell carcinoma (2); uterine carcinosarcoma (2); astrocytoma (1); Autoimmunity (1); bladder cancer (1); breast carcinoma (1); cervical squamous cell carcinoma (1); colon adenocarcinoma (1); endocervical adenocarcinoma (1); glioblastoma (1); kidney chromophobe (1); laryngeal squamous cell carcinoma (1); liver cancer (1); lupus (1); lupus-like syndrome (1); medullary thyroid cancer (1); medulloblastoma (1); mesothelioma (1); Obesity (1); oligodendroglioma (1); osteoporosis (1); ovarian serous cystadenocarcinoma (1); pheochromocytoma and paraganglioma (1); prostate adenocarcinoma (1); Splenomegaly (1); status epilepticus (1); type 2 diabetes (1); uterine corpus endometrial carcinoma (1).